ZNF519 (zinc finger protein 519)
Description:
May be involved in transcriptional regulation.
Synonyms: HsT2362; FLJ36809
Tractability: PROTAC: ubiquitination databases record sites on it.
Gene: Protein-coding gene on chromosome 18 (14,057,457 to 14,132,490, reverse strand). Ensembl gene ENSG00000175322.
Subcellular location: Nucleus
Subcellular location (Human Protein Atlas): Nucleoli
Pathways (Reactome):
Gene expression (Transcription): Generic Transcription Pathway; Regulation of endogenous retroelements by KRAB-ZFP proteins
Gene Ontology:
Molecular function: DNA-binding transcription factor activity, RNA polymerase II-specific; RNA polymerase II cis-regulatory region sequence-specific DNA binding
Biological process: regulation of DNA-templated transcription; regulation of transcription by RNA polymerase II
Cellular component: nucleus
Genetic constraint (gnomAD): Loss-of-function variants: 8 observed, 7.93 expected, observed/expected ratio (o/e) 1.01, 90% interval 0.59 to 1.72. That is too few expected variants to judge how well the gene tolerates losing a copy. Missense variants: 581 observed, 629.89 expected, observed/expected ratio (o/e) 0.92, 90% interval 0.86 to 0.99. Synonymous variants: 178 observed, 198.92 expected, observed/expected ratio (o/e) 0.89, 90% interval 0.79 to 1.01.
Homologues: Orthologues: chimpanzee ZNF519 (99% identical), mouse Zfp941 (43% identical). Paralogues in human: ZNF429 (51% identical), ZNF708 (50% identical), ZNF595 (50% identical), ZNF724 (49% identical), ZNF254 (48% identical), ZNF728 (48% identical), ZNF726 (47% identical), ZNF93 (47% identical), ZNF85 (47% identical), ZNF43 (46% identical), ZNF28 (46% identical), ZNF493 (45% identical), and 164 more.
Diseases named in the same sentence as ZNF519 in open-access papers:
ZNF519 is named in the same sentence as 6 diseases in open-access papers, as found by Europe PMC text mining. Sharing a sentence is not in itself a finding about the gene and the disease. The quoted sentences say what the papers report.
breast carcinoma (3 papers, 2022 to 2024). "GDF11, CD151, PAFAH1B2 and YTHDF2 may play a pivotal role in the predisposition of metastasis to the bone from breast cancer, whilst DPP9, FAS, ZNF519, RPP14 and FAU may be actively involved in the adaptative colonisation of metastatic breast cancer cells in bone." (PMID 35685372, 2022).
gastric cancer (1 paper, 2024). A primary or metastatic malignant neoplasm involving the stomach. "Noxa operates to stimulate ZNF519 in the downstream autophagy-animal signaling pathway, ultimately suppressing the advancement of gastric cancer cells." (PMID 38503887, 2024). "We have presented a schematic representation illustrating the impact of the miR-200b-3p-Noxa-ZNF519 axis on gastric cancer." (PMID 38503887, 2024). "The hsa-miR-200b-3p/Noxa/ZNF519 axis furnishes a solid theoretical foundation for unraveling the pathogenesis of gastric cancer and presents a promising avenue for the development of potential therapeutic targets in the fight against this disease." (PMID 38503887, 2024). "The current investigation sheds light on the pivotal role of the hsa-miR-200b-3p/Noxa/ZNF519 axis in elucidating the pathogenesis of gastric cancer, offering a promising avenue for targeted therapeutic interventions in the management of this challenging malignancy." (PMID 38503887, 2024). "According to our PCR findings, there is a sizable difference in ZNF519 expression between the NC and P-Noxa groups, prompting us to hypothesize that Noxa might exert its influence on the gastric cancer phenotype by regulating ZNF519." (PMID 38503887, 2024). "As anticipated, the proliferation of gastric cancer cells was restored upon downregulating ZNF519." (PMID 38503887, 2024). "The newly discovered Noxa inhibits the progression of gastric cancer cells by regulating the expression of ZNF519, which provides a theoretical basis for revealing the pathogenesis of GC and developing potential target therapies for GC." (PMID 38503887, 2024). "It was evident that the proliferation rate of the P-Noxa group was notably reduced in comparison to the negative control group, but the proliferation of gastric cancer cells was reinstated following ZNF519 silencing." (PMID 38503887, 2024).
Lissencephaly (1 paper, 2020). A spectrum of malformations of cortical development caused by insufficient neuronal migration that subsumes the terms agyria, pachygyria and subcortical band heterotopia. "The potential contribution of ZNF519 to the development of lissencephaly is also supported by the evidence that its expression is downregulated in mice with Lis1, Dcx, or Ywhae knockouts, whose gene mutations are causative for lissencephaly in humans." (PMID 32117005, 2020). "ZNF519 is a poly-ZNF highly expressed in brain and is involved in the etiology of microcephaly and lissencephaly." (PMID 32117005, 2020).
cancer (1 paper, 2025). A tumor composed of atypical neoplastic, often pleomorphic cells that invade other tissues. "Lastly, ZNF519 ranked fourth behind ZNF695, ZNF724P, and ZNF93 among KZFPs whose expression correlated positively with proliferation across 33 TCGA cancer types, pointing toward a general association between proliferation, i.e., repeated cell cycling, and elevated ZNF519 expression." (PMID 40555235, 2025).
ZNF519 also shares sentences with these, for which no sentence is quoted: tumour (2 papers); microcephaly (1).